LORICRIN (loricrin cornified envelope precursor protein)
Description:
Major keratinocyte cell envelope protein.
Synonyms: LOR
Tractability: Antibody: its Gene Ontology location is reachable by antibodies, with high confidence.
Gene: Protein-coding gene on chromosome 1 (153,259,687 to 153,262,124, forward strand). Ensembl gene ENSG00000203782.
Subcellular location: Cytoplasm; Nucleus, nucleoplasm
Pathways (Reactome):
Developmental Biology: Differentiation of Keratinocytes in Interfollicular Epidermis in Mammalian Skin; Formation of the cornified envelope
Gene Ontology:
Molecular function: protein binding; structural constituent of skin epidermis; structural constituent of cytoskeleton
Biological process: keratinocyte differentiation; peptide cross-linking; cytoskeleton organization
Cellular component: cornified envelope; cytoplasm; cytosol; nucleoplasm
Genetic constraint (gnomAD): Loss-of-function variants: 6 observed, 3.82 expected, observed/expected ratio (o/e) 1.57, 90% interval 0.78 to 1.94. That is too few expected variants to judge how well the gene tolerates losing a copy. Missense variants: 521 observed, 368.06 expected, observed/expected ratio (o/e) 1.42, 90% interval 1.32 to 1.52. Synonymous variants: 237 observed, 172.03 expected, observed/expected ratio (o/e) 1.38, 90% interval 1.24 to 1.53.
Homologues: Orthologues: pig LORICRIN (71% identical).
Diseases named in the same sentence as LORICRIN in open-access papers:
LORICRIN is named in the same sentence as 1 disease in open-access papers, as found by Europe PMC text mining. Sharing a sentence is not in itself a finding about the gene and the disease.
LORICRIN shares sentences with these, for which no sentence is quoted: Palmoplantar keratoderma (1 paper).